ENSG00000272297 (novel protein)
Gene: Protein-coding gene on chromosome 4 (186,426,546 to 186,555,328, reverse strand). Ensembl gene ENSG00000272297.
Genetic constraint (gnomAD): Loss-of-function variants: 3 observed, 2.38 expected, observed/expected ratio (o/e) 1.26, 90% interval 0.51 to 1.91. That is too few expected variants to judge how well the gene tolerates losing a copy. Missense variants: 56 observed, 51.07 expected, observed/expected ratio (o/e) 1.1, 90% interval 0.88 to 1.37. Synonymous variants: 31 observed, 28.12 expected, observed/expected ratio (o/e) 1.1, 90% interval 0.83 to 1.49.